ESRP1 (epithelial splicing regulatory protein 1)
Diseases named in the same sentence as ESRP1 in open-access papers (continued):
Sharing a sentence is not in itself a finding about the gene and the disease.
colon polyps (2 papers, 2017 to 2021). "Taken together, these results indicate that altered Esrp1-regulated mRNA splicing deregulates cIEC function and affects the development of intestinal disease in Triaka mice, through a mechanism reducing IEC proliferation." (PMID 28975893, 2017). "To shed more light on the mechanisms running in the background of our observation, i.e., overexpression of CD44v8-10 in colon polyps, we tested expression levels of RNA binding proteins ESRP-1 and ESRP-2 that are known to control ASP of CD44 in prostate epithelial cells." (PMID 34257584, 2021). "Only ESRP-1 gene was significantly upregulated in colon polyps." (PMID 34257584, 2021). "Our data indicated that an ESRP-1 dependent isoform switching mechanism misprint might be running in the background of ASP in colon polyps." (PMID 34257584, 2021). "Together, these data indicate an important role for ESRP1 in intestinal disease in humans and mice." (PMID 28975893, 2017). "Importantly, the lack of viable animal models so far has precluded analyzing the role of ESRP1-mediated AS for intestinal disease in vivo." (PMID 28975893, 2017). "Not surprisingly ESRP-1 is not upregulated in colon polyps of those patients who express the lowest levels of CD44v8-10." (PMID 34257584, 2021).
infection (2 papers, 2020 to 2024). The state of being infected such as from the introduction of a foreign agent such as serum, vaccine, antigenic substance or organism. "The most regulated gene (highest FC) is the epithelial splicing regulatory protein 1 (ESRP1) gene, which is regulated due to infection and vaccination." (PMID 38474155, 2024). "COLO320DM cells were infected with concentrated lentiviral particles over-expressing human ESRP1 ORF at a Multiplicity of Infection (MOI) of 1.5." (PMID 31963158, 2020).
digestive system tumors (1 paper, 2023). "And previous studies indicated that ESRP1 might play a completely different role in reproductive system tumors and digestive system tumors." (PMID 38114495, 2023).
ESRP1 also shares sentences with these, for which no sentence is quoted: head and neck carcinoma (4 papers); colon adeno-carcinoma (2); hepatocellular carcinoma (2); biliary atresia (1); congenital hypopituitarism (1); dysplasia (1); Infertility (1); Insulin resistance (1); lip (1); liver disease (1); metabolic syndrome (1); Obesity (1); primary biliary cholangitis (1); primary sclerosing cholangitis (1); rectal carcinoma (1); reproductive system tumors (1); resistant hypertension (1); sarcoma (1); Skeletal muscle atrophy (1); tubulovillous adenoma (1).